KLHL35 (kelch like family member 35)
Synonyms: FLJ33790
Tractability: Small molecule: it belongs to a druggable protein family. PROTAC: ubiquitination databases record sites on it.
Gene: Protein-coding gene on chromosome 11 (75,422,394 to 75,433,203, reverse strand). Ensembl gene ENSG00000149243.
Subcellular location (Human Protein Atlas): Centrosome; Nucleoplasm; Nucleoli fibrillar center
Gene Ontology:
Molecular function: protein binding; ubiquitin-like ligase-substrate adaptor activity
Biological process: proteasome-mediated ubiquitin-dependent protein catabolic process
Cellular component: Cul3-RING ubiquitin ligase complex; cytoplasm
Genetic constraint (gnomAD): Loss-of-function variants: 43 observed, 29.6 expected, observed/expected ratio (o/e) 1.45, 90% interval 1.14 to 1.84. The synonymous counts are far from expectation, so gnomAD's model fits this gene poorly and the ratio says little. Missense variants: 902 observed, 627.8 expected, observed/expected ratio (o/e) 1.44, 90% interval 1.36 to 1.52. Synonymous variants: 392 observed, 273.63 expected, observed/expected ratio (o/e) 1.43, 90% interval 1.32 to 1.56.
Homologues: Orthologues: chimpanzee KLHL35 (99% identical), macaque KLHL35 (96% identical), dog KLHL35 (90% identical), rabbit KLHL35 (89% identical), mouse Klhl35 (89% identical), pig KLHL35 (88% identical), rat Klhl35 (88% identical), guinea pig KLHL35 (75% identical), tropical clawed frog gdpd5 (51% identical). Paralogues in human: KLHL24 (44% identical), KLHL6 (36% identical), KLHL21 (30% identical), KLHL5 (28% identical), KLHL12 (28% identical), KLHL29 (28% identical), KLHL30 (28% identical), KLHL20 (27% identical), KLHL2 (27% identical), KLHL4 (27% identical), KLHL40 (27% identical), KLHL1 (27% identical), and 42 more.
Diseases named in the same sentence as KLHL35 in open-access papers:
KLHL35 is named in the same sentence as 12 diseases in open-access papers, as found by Europe PMC text mining. Sharing a sentence is not in itself a finding about the gene and the disease. The quoted sentences say what the papers report.
colon cancer (3 papers, 2022 to 2023). "KLHL35 is highly expressed in colon cancer tissues compared with normal samples and is associated with poor prognosis in colon cancer patients." (PMID 37020524, 2023). "The clinical relevance of CSTL1, FJX1, IER5L, and KLHL35 in 521 colon cancer cases was assessed, showing the expression level of CSTL1 mRNA was higher than that in normal tissues, and the expression levels of PD, SD, PR, and CR were higher than those in normal tissues." (PMID 35928453, 2022).
colorectal cancer (2 papers, 2022 to 2025). A primary or metastatic malignant neoplasm that affects the colon or rectum. "Receiver operating characteristic (ROC) curve analysis suggested promising but exploratory diagnostic value for KLHL35, with area under the curve (AUC) values exceeding 0.9 in colorectal cancer." (PMID 41114922, 2025). "Comprehensive analysis of RNA sequencing data from The Cancer Genome Atlas (TCGA) and protein expression data from the Human Protein Atlas (HPA) revealed significant overexpression of KLHL35 in 13 tumor types, including colorectal cancer." (PMID 41114922, 2025). "This study investigates the expression patterns and clinical relevance of KLHL35 (Kelch-Like Family Member 35) across various cancer types, with a focus on colorectal cancer." (PMID 41114922, 2025). "The immunohistochemical staining showed that the expression of FJX1 in colorectal cancer tissues was significantly different from that in normal colon tissues, while the protein level of KLHL35 was not significantly different." (PMID 35928453, 2022).
hepatocellular carcinoma (2 papers, 2016 to 2021). A malignant tumor that arises from hepatocytes. "At the same time, hypermethylation of the gene KLHL35 has also been demonstrated to be associated with the development of hepatocellular carcinoma." (PMID 34199440, 2021). "In particular, KLHL35 is hypermethylated in hepatocellular carcinoma, renal cell carcinoma, and various other cancers, based on data from The Cancer Genome Atlas." (PMID 27383059, 2016).
renal cell carcinoma (2 papers, 2016 to 2022). "Methylation of KLHL35 was significantly higher in cancer tissue than in noncancerous tissue of liver cancer and renal cell carcinoma." (PMID 35884544, 2022).
breast carcinoma (1 paper, 2019). "Six hub genes, including IFIT1, ISG15, IFI6, GOLM5, KLHL35, and OAS2, were associated with the total survival probability in breast cancer patients." (PMID 30646630, 2019). "Hub gene selection and its relation to survival probability indicated that 10 hub genes (except KLHL35) were increased in both breast cancer and samples treated with bufadienolide-like chemicals." (PMID 30646630, 2019). "Further analysis of the correlation between the hub genes and the total survival time in breast cancer indicated that the high expression of GOLM5, KLHL35, and OAS2 was associated with a better survival probability." (PMID 30646630, 2019).
lung adenocarcinoma (1 paper, 2025). A carcinoma that arises from the lung and is characterized by the presence of malignant glandular epithelial cells.
tumor (7 papers, 2015 to 2025). "The specific function of KLHL35 remains unclear, but recent investigations have demonstrated its association with DNA methylation and tumor mutation burden in cancers." (PMID 38478169, 2024). "The remaining four PCRGs (ASPDH1, PPP1R13L, PMAIP1, and KLHL35) showed higher expression levels in tumor tissues than in pericardial tissues." (PMID 37190215, 2023). "The Mann-Whitney U test (Wilcoxon rank-sum test) for unpaired samples showed the expression of CSTL1, FJX1, IER5L, and KLHL35 in tumor tissue was higher than that in normal tissue." (PMID 35928453, 2022). "FJX1 protein levels in the tumor were higher than in normal tissue, while KLHL35 protein levels were undetectable in both tumor and normal tissues, and no immunohistochemistry data for the remaining two genes were available." (PMID 35928453, 2022). "ANKRD13B, ISG15, KBTBD12, KLHL35, and UHRF1 were upregulated in tumor samples; DCUN1D5, HCK, and SOCS3 were downregulated in tumor than in normal samples." (PMID 35884544, 2022).
cancer (6 papers, 2016 to 2025). A tumor composed of atypical neoplastic, often pleomorphic cells that invade other tissues. "In vitro assays confirmed KLHL35’s role in promoting cancer cell proliferation, invasion, and migration." (PMID 41114922, 2025). "Taken together, epigenetic dysregulation of KLHL35 appears to be a feature shared across multiple cancers." (PMID 27383059, 2016). "The promoter methylation levels of FJX1, KLHL35, and IER5L in primary malignant tumors were higher than those in normal tissues." (PMID 35928453, 2022). "Eight of these had decreased expression in cancer (KLHL3, KLHL4, KLHL13, KLHL14, KLHL29, KLHL30, KLHL32, and KLHL33) while four genes (ENC1, KLHL12, KLHL17, and KLHL35) had patterns of up-regulated gene expression." (PMID 30647843, 2018).
KLHL35 also shares sentences with these, for which no sentence is quoted: metastatic cancers (2 papers); leprosy (1); liver cancer (1); metastatic tumor (1).